ALB (albumin)
Diseases named in the same sentence as ALB in open-access papers (continued):
Sharing a sentence is not in itself a finding about the gene and the disease.
kidney disease (continued). "In addition, albumin is the most common protein in urine in a variety of kidney diseases, and urinary albumin levels can be accurately measured within the normal range." (PMID 39055699, 2024). "Fifth, the semiquantitative scoring of IgG or albumin uptake (1+ to 3+, etc.)may be unreliable due to subjectivity and the focal nature of proteinuric renal diseases." (PMID 39544696, 2024). "Additionally, kidney disease—is measured by the urinary albumin-to-creatinine ratio (ACR) which is defined as the ratio of urine albumin-to-urine creatinine." (PMID 38347632, 2024). "Excess albumin in the urine is a sign of kidney disease known as Albuminuria." (PMID 36829884, 2023). "Low vitamin D has been shown to correlate with reduced serum albumin, particularly in renal disease and albuminuria, but no cause for the correlations in UC more so than CD is immediately evident, particularly as more patient episodes were CD." (PMID 38162852, 2023). "In patients without pre-existing renal disease, all associations remained except those with platelet count, serum creatinine, and urinary albumin to creatinine ratio." (PMID 37748493, 2023). "Proteomic indicators may enable more precise and early diagnosis of renal disease compared to currently used indicators like creatinine and urine albumin." (PMID 38116359, 2023). "We previously synthesized an albumin–thioredoxin fusion protein (Alb–Trx), which has a longer plasma half-life than thioredoxin, and reported its effectiveness in the treatment of respiratory and renal diseases." (PMID 37298708, 2023). "Albuminuria is commonly noted in severe renal disease, and in such cases albumin may promote apoptosis of the tubular epithelial cells, leading to the progressive worsening of the pathology." (PMID 36979342, 2023). "In conclusion, this article presents a comprehensive study on the development of an aptasensor coupled with a high-accuracy, low-cost, portable fluorometer and a smartphone application for the measurement of albumin in urine samples, enabling the early detection of kidney disease." (PMID 37754110, 2023). "Kidney disease progression is actually slower in albumin knockout mice than wild-type mice." (PMID 36979342, 2023). "Lower levels of albumin are generally due to inflammation, liver or kidney diseases." (PMID 35793325, 2022). "However, it is difficult to differentiate an accumulation induced by the absorption of lipids bound to albumin in a context of advanced, and sometimes proteinuric, kidney disease, from a primary dysfunction of FA metabolism involved in kidney injury." (PMID 35998043, 2022). "Currently, DN research relies on traditional diagnostic techniques, such as the histological assessment of collagen deposition and quantification of serum/urine biomarkers (e.g., creatinine, blood urea nitrogen (BUN), albumin, and cytokines) to confirm kidney disorders." (PMID 35055081, 2022). "Another observation from our longitudinal analysis was that there was a very strong connection between albumin and vitamin 1,25(OH)2D3 levels, which is known for renal diseases, and in the case of CRC, with the most probability it is connected to disease progression." (PMID 35158926, 2022). "Fifthly, albumin levels are related to presence of liver and kidney diseases." (PMID 36684211, 2022). "Together, these data support a hypothesis in which circulating APOL1 enters the urine similar to albumin and may play a role in the development and progression of kidney disease." (PMID 36279295, 2022). "It is essential to measure microalbuminuria precisely as even slight increases in urine albumin could predict the early changes in the course of renal disorders." (PMID 36046275, 2022). "The albumin to creatinine ratio (ACR) is commonly used for identifying kidney disease." (PMID 36501396, 2022).
kidney disease (continued). "As chronic albuminuria is associated with worsening kidney disease and albumin has been implicated in tubular epithelial injury, we investigated whether albumin participates in CRS‐1, and whether CRS‐1 alters renal albumin handling." (PMID 35150207, 2022). "However, physicians should be cautious in evaluating nutritional status with serum albumin levels because of the effect of age and various conditions, including inflammation and liver or kidney diseases." (PMID 35268404, 2022). "In general, the pro-inflammatory state is crucial for development and progression of different kidney diseases; thus, evaluating not only albumin levels but also its redox state could be crucial in the prognosis of kidney disease." (PMID 33800425, 2021). "Thus, the level of Cys34-cysteinylated albumin is significantly increased in patients who suffer from DM, liver and kidney diseases." (PMID 34638659, 2021). "In addition, the binding of ARP to human albumin under conditions of oxidation stress in kidney diseases was examined using chloramine-T oxidized human albumin." (PMID 34822595, 2021). "However, recent research has shown that lab-on-paper platforms provide a feasible means of detecting early-stage kidney disease by evaluating the concentrations of creatinine (Cre) and albumin (Alb), micro-albumin and protein, and uric acid in urine samples." (PMID 34436062, 2021). "Moreover, oxidized albumin in kidney disease patients is independently correlated with higher plasma levels of transforming growth factor beta (TGF-β1), tumor necrosis factor (TNF-α), and interleukin (IL)-1β and IL-6." (PMID 33800425, 2021). "However, caveolae have received increasing attention as a metabolic platform that mediates the endocytosis of albumin, cholesterol, and glucose, participates in cellular metabolic reprogramming and is involved in the progression of kidney disease." (PMID 34955837, 2021). "Moreover, a double-blind, placebo-controlled trial enrolling patients from 116 research centers showed that Dapa decreases the urine albumin-to-creatinine ratio and slows kidney disease progression in patients with moderate-to-severe CKD." (PMID 35069210, 2021). "However, in humans with kidney disease, acute oxidative stress leads to a transient increase in protein excretion, including increased albumin excretion." (PMID 33031394, 2020). "In the line with these findings Kidney Disease Improving Global Outcomes (KDIGO) clinical practice guidelines recommend a BP target of <140/90 mmHg in those with albumin excretion <30 mg/24 h and a BP goal of <130/80 mmHg in those with albumin excretion >30 mg/24 h." (PMID 32582768, 2020). "As a marker of the severity of kidney disease, urinary albumin may reflect the degree of muscle weakness in patients with kidney disease." (PMID 32405506, 2020). "However, there are still arguments in favor of simply using albumin as a nutritional marker in assessing kidney diseases." (PMID 31035482, 2019). "A reduction in the percentage of oxidized albumin may also be a target for the prevention of renal diseases." (PMID 31197181, 2019). "In albuminuric/proteinuric kidney disease, the damaged glomerulus allows albumin-bound FAs to be filtered and gain access to the previously unexposed proximal tubule luminal surface, where aberrant FA reabsorption could then occur." (PMID 31373312, 2019). "Diabetic nephropathy is both a vascular and a renal disease and affected patients display, even at early stage of nephropathy clinically marked by elevated urinary albumin excretion and conserved renal function, increased incidence of cardiovascular events, especially myocardial infarction." (PMID 31316987, 2019). "Both serum albumin and hemoglobin levels decreased as the stage of the kidney disease progressed." (PMID 30761853, 2019).
kidney disease (continued). "A total of 5148 patients (73.8%) had prevalent kidney disease (defined as eGFR < 60 mL/min/1.73 m2 or macroalbuminuria [albumin-to-creatinine ratio > 300 mg/g]) and 3990 patients (57.2%) had established CV disease with increased albuminuria; these characteristics were not mutually exclusive." (PMID 29540217, 2018). "In a recent meta-analysis, the authors published that statins significantly reduce albuminuria, the rate of excretion of urinary albumin, that the efficacy of renal function is dependent on the length of history of DM, and that the effect is better in type 2 DM with nephropathy." (PMID 29808088, 2018). "The U.S. National Kidney Foundation recommends three basic tests to screen for kidney disease: a quantitative test for protein or albumin in the urine (proteinuria), a calculation of glomerular filtration rate (GFR) based on a serum creatinine measurement, and a blood pressure measurement." (PMID 28409224, 2017). "Renal disease markers included increases of urinary albumin excretion and urine volume with age." (PMID 29211750, 2017). "BMI, LVEF, hemoglobin, albumin and pre-procedural Modification of Diet in Renal Disease estimated glomerular filtration rate (MDRD eGFR) levels were lower, while the level of pre-procedural plasma glucose, uric acid and phosphorus were higher in the CI-AKI group." (PMID 27775043, 2016). "The existence of urinary albumin is a cardinal feature of kidney disease in general." (PMID 24900991, 2014). "Our results indicate that LTs mediate, at least in part, tubulointerstitial injury induced by albumin overload, which could be important in the progression of renal disease." (PMID 25302946, 2014). "On the other hand, it has been shown that overload of albumin in the proximal tubule promotes tubule interstitial injury leading to progression of renal disease through different pathways, including the accumulation of pro-inflammatory chemokines and cytokines such as TNF-α and IL-6." (PMID 24736406, 2014). "Neither BMI nor albumin was associated with the progression of kidney disease and the relationship of homoarginine with CKD progression was still significant after adjustments for albumin and BMI (HR 1.44, 95% CI 1.01–2.05, p = 0.045)." (PMID 23691067, 2013). "In our additional analyses, neither BMI nor albumin were associated with the progression of kidney disease and it is important to note that the relationship of homoarginine with progression was still significant after adjustments for albumin and BMI." (PMID 23691067, 2013). "Patients with more advanced CKD had lower hemoglobin (ρ = −0.40; p<0.001), albumin (ρ = −0.35; p<0.001), and calcium (ρ = −0.25; p<0.001) serum concentration while phosphorus levels were directly correlated with the severity of renal disease (ρ = 0.45; p<0.001)." (PMID 23173709, 2012). "Excretion of albumin into the urine must be detected as early as possible, because once pathological thresholds are reached, progression to advanced renal disease may result." (PMID 20838718, 2010). "The low serum albumin value in this case may be indicative of a kidney disorder, in spite of normal serum creatinine values." (PMID 19331658, 2009). "Furthermore, in 2021, a retrospective case-control study suggested that Cys-albumin may serve as a biomarker for the progression of kidney disease in individuals with type 2 diabetes." (PMID 40502874, 2025). "Notably, both albumin and its redox state levels could be crucial in the progression of kidney disease." (PMID 40108938, 2025). "The disparity between the high degree of albuminuria and the lower prevalence of CKD estimated by eGFR may be attributed to the higher occurrence of early-stage kidney disease, where kidneys maintain filtration but become more permeable to albumin, leading to albuminuria." (PMID 38347632, 2024).
kidney disease (continued). "It is possible that the individuals with kidney disease in the present study might have low in situ rate of glycation of serum proteins due to less availability of albumin, or these individuals might excrete more serum proteins in the urine due to their kidney dysfunction." (PMID 38965604, 2024). "While HDL is generally considered to have a protective effect on the glomerular filtration barrier, in specific kidney diseases, elevated HDL levels may be associated with increased oxidative stress and inflammation in the glomerular basement membrane, leading to albumin leakage." (PMID 39491271, 2024). "Moreover, low serum albumin levels may rely on several mechanisms involving inflammation, nutritional issues, and renal disease." (PMID 37484969, 2023). "However, decreased albumin may be attributed to several factors, including malnourishment, gastrointestinal diseases, intestinal parasitism, increased catabolism, and renal diseases." (PMID 35812844, 2022). "The characteristics that were selected for investigating whether there is a risk of developing kidney disease or not are related to age, blood pressure, specific gravity, albumin, etc.." (PMID 36433212, 2022). "Notably, the urinary L-FABP levels of diabetic patients with normoalbuminuria were significantly higher (p<0.001) than those of the normal control, suggesting that urinary L-FABP is an earlier indicator than urinary albumin in the detection of renal disorders in diabetic patients." (PMID 33033456, 2020). "Thus, manipulate the response of TECs to excessive albumin to reduce the toxicity of protein might represent a novel direction for therapy of kidney disease in addition to lowering albuminuria." (PMID 32641688, 2020). "Finally, in all multivariate logistic regression models, low serum albumin, high proteinuria and congential cause of kidney disease were associated with rapid progression of CKD (data not shown)." (PMID 28033375, 2016). "We used Kidney Disease: Improving Global Outcomes (KDIGO) criteria to define CKD progression and defined CKD remission as the absence of diagnostic criteria (estimated glomerular filtration rate [eGFR] >60 ml/min/1.73 m2 and urine albumin-to-creatinine ratio [uACR] <3 mg/mmol) at any study visit." (PMID 27648564, 2016). "The fact that albuminuria was independently associated with increased IOP in patients without kidney disease suggests that urinary albumin excretion might be an independent and more relevant pathophysiological surrogate of increased IOP than GFR." (PMID 24788677, 2014). "In part, this correlation is due to the fact that the overload of albumin in proximal tubule (PT) cells induces proinflammatory and profibrotic effects and contributes directly to the development of tubulointerstitial injury, and, consequently to progression of renal disease." (PMID 25302946, 2014). "Serum albumin levels may depend on renal disease state under the most favorable conditions." (PMID 20927340, 2010). "The urine albumin-to-creatinine ratio (UACR) is a sensitive indicator of proteinuria and is frequently used to screen for kidney disease in its early stage." (PMID 40196454, 2025). "In addition, using a single GFR/albumin level may lead to misclassification of kidney disease." (PMID 40424235, 2025). "The top 18 indicators ranked by their importance in the model were as follows: MAP, chronic hypertension, UIBC, kidney disease, proteinuria, BMI, TIBC, HDL-C, ApoA1, ALB, Fn, C4, CHO, GLO, Cr, Fe, TG and Ca." (PMID 40002760, 2025). "When compared with other available measures of albuminuria (e.g., 24‐h urinary albumin excretion and urinary albumin concentration), UACR demonstrates the highest accuracy for predicting kidney events in individuals with kidney disease and T2D." (PMID 39739537, 2025).
kidney disease (continued). "The results prompt the need for further studies more deeply addressing biochemical processes leading to albumin changes and the clinical utility of eHA parameters for the diagnosis and prognosis of T2DM-related kidney disease." (PMID 38542146, 2024). "Accordingly, SDS–PAGE analysis of urine samples showed a massive increase in serum albumin (also known as albuminuria) in the animals treated with the vectors targeting Hgd and Gstz1 following NTBC removal, indicative of kidney disease." (PMID 39178380, 2024). "We used albumin-to-creatinine ratio (ACR) and estimated glomerular filtration rate (eGFR) to estimate the prevalence of kidney disease in the Tiwi population (N = 492) in comparison to the UK Biobank (UKBB) (N = 134,724) database." (PMID 38347632, 2024). "The target independent variable was serum albumin measured before surgery after hospital admission, and the dependent variable was AKI, defined in accordance with the Kidney Disease Improving Global Outcomes (KDIGO) criteria." (PMID 36836115, 2023). "However, the study did not simultaneously measure urinary albumin concentrations and thus could not discern the contribution of urinary albumin loss—an established prognostic marker and potential confounder of kidney disease." (PMID 36922779, 2023). "We also reported that brief periods of hyperphagia increase renal disease of female UC Davis ZUC rats as judged by histological studies and urinary albumin excretion." (PMID 29211750, 2017). "Secondary outcomes include health-related quality of life (assessed by the Kidney Disease Quality of Life instrument; KDQOL), self-efficacy (assessed by General Self-Efficacy Scale) and clinical indices (e.g. albumin and haemoglobin levels)." (PMID 27612446, 2016). "Urinary albumin excretion is routinely assessed in the diagnosis of renal injury, due its urinary appearance prior to GFR decline in different renal diseases." (PMID 25875363, 2015). "In other renal diseases, urinary MCP-1 has been correlated with urinary albumin excretion rate, glomerular filtration rate reduction and other features of renal injury." (PMID 24265821, 2013). "Further, none of the mice in the current study developed kidney disease, as assessed by normal urine albumin excretion and lack of renal pathology." (PMID 40459058, 2025). "In line with recent KDIGO and Kidney Disease Outcomes Quality Initiative (KDOQI) guidelines, our results support the use of serum albumin as a pragmatic prognostic marker within a broader, multidimensional assessment of nutritional and inflammatory status in ESRD." (PMID 41552166, 2025). "We will not evaluate the patients’ primary kidney disease or other health problems potentially affecting the blood protein level (albumin)." (PMID 40570345, 2025). "It is not surprising that the addition of ruxolitinib to UCB-Tregs did not add to their existing benefit of controlling systemic renal disease manifestations, as measured by urine albumin/creatinine ratio as well as anti-dsDNA IgG Ab." (PMID 39975551, 2025). "Patients with VTE have lower albumin levels compared with non-VTE controls in patients with chronic liver disease or kidney disease." (PMID 40168285, 2025). "Patients with specific risk factors, such as abnormal body temperature (≤36.0 or ≥38.5 °C), chilling sensations, kidney disease, a history of drug reactions, elevated CRP (≥32 mg/L), elevated PCT (≥1.00 ng/ml), and low albumin (≤31.0 g/L), require close monitoring for BSI development." (PMID 39006018, 2024). "According to the nomenclature of kidney function and disease from the Kidney Disease Improving Global Outcomes (KDIGO) consensus conference, albuminuria is defined as a urinary albumin excretion rate (AER) >10 mg/d or an albumin–creatinine ratio (ACR) >10 mg/g." (PMID 38337471, 2024).